ITGBL1 (integrin subunit beta like 1)
Diseases named in the same sentence as ITGBL1 in open-access papers (continued):
Sharing a sentence is not in itself a finding about the gene and the disease.
tumor (continued). "The results demonstrated that CRC patients with lower ITGBL1 mRNA-expressing tumors had improved prognosis, and the mRNA levels of ITGBL1 were closely associated with CRC TNM (tumor, lymph node, and metastasis) stages, and liver and lung metastasis." (PMID 32139701, 2020). "We noticed that the expression of one gene, KRT17, which has been reported to stimulate the migration and invasion of the tumour cells, was significantly increased following ITGBL1 overexpression." (PMID 32537856, 2020). "We provide compelling evidence to establish a signaling pathway by which tumor-derived ITGBL1-enriched EVs convert primary fibroblasts to CAFs via binding to TNFAIP3 and activating the NF-κB signaling pathway." (PMID 32139701, 2020). "Strikingly, we found that the SMMC‐7721 cells with ITGBL1 overexpression significantly enhanced the tumour growth abilities compared to the cells from the control group." (PMID 32537856, 2020). "Similar to fibroblasts educated by ITGBL1-enriched EVs, primary CAFs with high ITGBL1 expression promoted tumorigenicity, tumor stemness, metastatic growth, and EMT." (PMID 32139701, 2020). "ITGBL1 was involved in the formation of tumor microenvironment, but the molecular mechanism of ITGBL1 in CRC remained unclear." (PMID 32211321, 2020). "The Ki‐67 staining of the xenografts suggested that the tumour with the ITGBL1‐overexpressing SMMC‐7721 cells had higher proliferation abilities than the control SMMC‐7721 cells." (PMID 32537856, 2020). "Thirty‐four days after the injection, the tumour weight of the Lv‐ITGBL1‐transfected SMMC‐7721 cells were markedly higher than the Lv‐control‐transfected cells in the mice." (PMID 32537856, 2020). "Many cytokines, such as ITGBL1 and ET-1, facilitate processes in the tumor cells, such as recruiting, residing, and growth in the bone and further stimulate osteoclast maturation in the bone microenvironment to form bone metastatic lesions." (PMID 29416737, 2018). "Overall, these experiments suggested that targeting ITGBL1 inhibition could block M2-type macrophage polarization and improve lymphocytic immunity, resulting in anti-tumor properties in vitro." (PMID 39840822, 2025). "The effect of ITGBL1 on COAD tumor growth was examined using a xenograft tumor model." (PMID 39840822, 2025). "Furthermore, after injecting for 4 weeks, the tumor weights of mice injected with ITGBL1-silenced cells were significantly decreased." (PMID 35584452, 2022). "Additionally, ITGBL1 increased the expression levels of EMT-associated genes and tumor cells migration." (PMID 32139701, 2020). "Moreover, the mRNA expression of ITGBL1 in human CRC tumor samples had strong correlation with the ITGBL1 levels in corresponding plasma EVs of CRC patients." (PMID 32139701, 2020). "In the univariate analysis, the clinicopathological characteristics including AFP (P = .038), tumour number (P < .001), BCLC stage (P < .001), vascular invasion (P = .003) and ITGBL1 expression (P = .014) were significantly associated with the OS in HCC patients." (PMID 32537856, 2020). "Hence, ITGBL1 is closely associated with the metastatization of CRC and involved in the tumor microenvironment." (PMID 32211321, 2020). "Importantly, the experimental lung and liver metastasis model, and the cecum orthotopic tumor metastasis model validate ITGBL1-enriched EVs accelerated metastatic growth." (PMID 32139701, 2020). "We found that ITGBL1 expression level was significantly associated with the tumour encapsulation status (P = .037), but not other clinicopathological characteristics." (PMID 32537856, 2020).
tumor (continued). "However, ITGBL1 was down-regulated in non-small cell lung cancer (NSCLC) tissues as a novel tumor suppressor in NSCLC progression." (PMID 29285211, 2017). "Similarly, ITGBL1 is involved in tumor cell invasion and metastasis through the KRAS/EMT pathway." (PMID 33718128, 2021). "The results showed that after injection of ITGBL1-silenced PANC-1 cells, tumor volumes of mice were decreased over time." (PMID 35584452, 2022). "Further, the Western blotting results also suggested that the protein expression level of ITGBL1 was upregulated in eight paired HCC tumour tissues, compared with the adjacent non‐tumour tissues." (PMID 32537856, 2020). "In the current study, we found both the protein and mRNA levels of ITGBL1 were increased in HCC tumour tissues, compared with the adjacent non‐tumour tissues." (PMID 32537856, 2020). "IHC analysis performed with these paired tissues showed more ITGBL1-positive tissues in tumor tissues than in nontumor tissues (P < 0.01)." (PMID 35596183, 2022). "In eight pairs of matched samples, the expression of ITGBL1 increased in tumor tissues relative to adjacent nontumor tissues, accounting for 61.5% (8/13 patients); however, only two patients had low expression in GC tissues (P < 0.05)." (PMID 35596183, 2022). "Subsequently, to confirm the effects of ITGBL1 on HCC tumour growth in vivo, SMMC‐7721 cells with or without stable ITGBL1 overexpression were subcutaneously injected into the nude mice and the tumour size of the xenografts were measured." (PMID 32537856, 2020). "We found that ITGBL1 was highly expressed in HCC tumour tissues, whereas weak or negative expression of ITGBL1 was observed in the adjacent non‐tumour tissues (Wilcoxon's signed‐rank test, P < .001)." (PMID 32537856, 2020). "ITGBL1 is located in the ECM and related to the tumor microenvironment." (PMID 32211321, 2020). "Owing to the existence of autoimmune regulation in C57Bl/6 mice, the regulatory effect of ITGBL1-enriched EVs on EVs incorporation, EVs fusion with recipient cells, the pre-metastatic niche formation, and tumor metastatic growth may not be identical and warrants future investigation." (PMID 32139701, 2020).
ITGBL1 also shares sentences with these, for which no sentence is quoted: idiopathic pulmonary fibrosis (3 papers); fibrosis (2); pancreatic cancer (2); acute myeloid leukemia (1); adenoma (1); colon adenocarcinoma (1); colorectal tumors (1); COVID-19 (1); diffuse gastric adenocarcinoma (1); Ewing sarcoma (1); gastric intestinal type adenocarcinoma (1); glioblastoma (1); heart failure (1); Intellectual disability (1); liver cancer (1); lung carcinoma (1); Myocardial fibrosis (1); Nystagmus (1); osteoporosis (1); osteosarcoma (1); renal cell carcinoma (1).